TIMM21 (translocase of inner mitochondrial membrane 21)
Description:
Participates in the translocation of transit peptide-containing proteins across the mitochondrial inner membrane. Also required for assembly of mitochondrial respiratory chain complex I and complex IV as component of the MITRAC (mitochondrial translation regulation assembly intermediate of cytochrome c oxidase complex) complex. Probably shuttles between the presequence translocase and respiratory-chain assembly intermediates in a process that promotes incorporation of early nuclear-encoded subunits into these complexes.
Synonyms: C18orf55; TIM21; HSPC154
Tractability: Antibody: UniProt predicts a signal peptide or a membrane-spanning region. PROTAC: ubiquitination databases record sites on it; its protein half-life has been measured.
Gene: Protein-coding gene on chromosome 18 (74,148,512 to 74,160,531, forward strand). Ensembl gene ENSG00000075336.
Subcellular location: Mitochondrion membrane
Pathways (Reactome):
Metabolism: Complex IV assembly
Protein localization: Mitochondrial protein import
Gene Ontology:
Molecular function: protein binding
Biological process: mitochondrial respiratory chain complex I assembly; mitochondrial respiratory chain complex IV assembly; protein import into mitochondrial matrix; intracellular protein transport
Cellular component: mitochondrion; TIM23 mitochondrial import inner membrane translocase complex; mitochondrial inner membrane; mitochondrial intermembrane space; mitochondrial membrane
Genetic constraint (gnomAD): Loss-of-function variants: 29 observed, 28.48 expected, observed/expected ratio (o/e) 1.02, 90% interval 0.76 to 1.39. The upper end of that interval is the gene's LOEUF score, 1.39, which puts it in group 5 of 6, group 1 being the genes least tolerant of losing a copy. Missense variants: 251 observed, 274.87 expected, observed/expected ratio (o/e) 0.91, 90% interval 0.82 to 1.01. Synonymous variants: 110 observed, 109.17 expected, observed/expected ratio (o/e) 1.01, 90% interval 0.86 to 1.18.
Homologues: Orthologues: chimpanzee TIMM21 (99% identical), macaque TIMM21 (94% identical), pig TIMM21 (78% identical), dog TIMM21 (76% identical), guinea pig TIMM21 (76% identical), rat Timm21 (71% identical), mouse Timm21 (68% identical), tropical clawed frog timm21 (54% identical), zebrafish timm21 (46% identical), Drosophila melanogaster CG7382 (32% identical), Caenorhabditis elegans F56B3.11 (23% identical).
Diseases named in the same sentence as TIMM21 in open-access papers:
TIMM21 is named in the same sentence as 4 diseases in open-access papers, as found by Europe PMC text mining. Sharing a sentence is not in itself a finding about the gene and the disease. The quoted sentences say what the papers report.
leukemia (1 paper, 2016). A malignant (clonal) hematologic disorder, involving hematopoietic stem cells and characterized by the presence of primitive or atypical myeloid or lymphoid cells in the bone marrow and the blood. "Furthermore, we also identified a strong correlation in ETV6/RUNX1-positive leukemias between NETO1 and its adjacent, bidirectional lncRNA lnc-TIMM21-5 (r = 0.89) as well as between LRP8 and lnc-CPT2-7 (r = 0.70)." (PMID 27650541, 2016).
TIMM21 also shares sentences with these, for which no sentence is quoted: gastric adenocarcinoma (1 paper); glioma (1); ovarian carcinoma (1).